PSTPIP2 (proline-serine-threonine phosphatase interacting protein 2)
Description:
Binds to F-actin. May be involved in regulation of the actin cytoskeleton (By similarity).
Synonyms: MAYP
Tractability: Antibody: UniProt places it where antibodies can reach, with medium confidence; its Gene Ontology location is reachable by antibodies, with medium confidence; the Human Protein Atlas places it where antibodies can reach. PROTAC: ubiquitination databases record sites on it; its protein half-life has been measured.
Gene: Protein-coding gene on chromosome 18 (45,983,536 to 46,072,296, reverse strand). Ensembl gene ENSG00000152229.
Subcellular location: Cytoplasm; Membrane
Subcellular location (Human Protein Atlas): Plasma membrane; Cytosol
Gene Ontology:
Cellular component: cytoplasm; plasma membrane; cytoskeleton; cytosol; membrane
Genetic constraint (gnomAD): Loss-of-function variants: 29 observed, 50.69 expected, observed/expected ratio (o/e) 0.57, 90% interval 0.43 to 0.78. The upper end of that interval is the gene's LOEUF score, 0.78, which puts it in group 3 of 6, group 1 being the genes least tolerant of losing a copy. Missense variants: 270 observed, 362.31 expected, observed/expected ratio (o/e) 0.75, 90% interval 0.67 to 0.82. Synonymous variants: 113 observed, 123.19 expected, observed/expected ratio (o/e) 0.92, 90% interval 0.79 to 1.07.
Homologues: Orthologues: chimpanzee PSTPIP2 (99% identical), macaque PSTPIP2 (96% identical), pig PSTPIP2 (91% identical), rabbit PSTPIP2 (90% identical), mouse Pstpip2 (87% identical), rat Pstpip2 (87% identical), dog PSTPIP2 (86% identical), guinea pig PSTPIP2 (83% identical), tropical clawed frog PSTPIP2 (63% identical), zebrafish pstpip2 (55% identical), Drosophila melanogaster CG8176 (19% identical), Caenorhabditis elegans fcho-1 (14% identical). Paralogues in human: PSTPIP1 (45% identical), FCHO2 (23% identical), FCHO1 (22% identical), GAS7 (19% identical), SGIP1 (10% identical).
Diseases named in the same sentence as PSTPIP2 in open-access papers:
PSTPIP2 is named in the same sentence as 45 diseases in open-access papers, as found by Europe PMC text mining. Sharing a sentence is not in itself a finding about the gene and the disease. The quoted sentences say what the papers report.
chronic multifocal osteomyelitis (10 papers, 2013 to 2025). "Their findings hint at the promising potential of dietary interventions aimed at modulating the gut microbiota as a therapeutic strategy for the treatment of chronic multifocal osteomyelitis (CMO) arising from PSTPIP2 deficiency." (PMID 39660128, 2024). "In this strain, the loss of adaptor protein PSTPIP2 leads to the autoinflammatory disease chronic multifocal osteomyelitis." (PMID 36605205, 2022). "Mutations of PSTPIP2 gene are associated with the auto-inflammatory disorder chronic multifocal osteomyelitis in mice." (PMID 30564127, 2018). "Currently, PSTPIP2 has been shown to play important roles in autoinflammatory diseases, including chronic recurrent multifocal osteomyelitis (CRMO) and sepsis." (PMID 34262554, 2021). "PSTPIP2 has been known for its principal role in the development of inflammatory disorder described as chronic multifocal osteomyelitis in mice, where its reduced expression or complete absence is the main cause of the disease." (PMID 30564127, 2018). "Two strains have been reported: Chronic multifocal osteomyelitis (CMO) mice carry a spontaneous mutation in Pstpip2 (p.L98P), in lupo mice a Pstpip2 mutation was chemically induced (p.I282N)." (PMID 24359092, 2013). "In addition, in our recent work on Pstpip2-KO induced autoinflammatory disease, chronic multifocal osteomyelitis, and Ncf2-KO–induced chronic granulomatous disease, we demonstrated that genetic loss of Morrbid mitigated these 2 autoinflammatory diseases too." (PMID 40906528, 2025). "Additionally, the emerging role of PSTPIP2 in modulating the gut microbiome in chronic multifocal osteomyelitis presents a novel perspective for disease treatment." (PMID 39660128, 2024). "A missense mutation (L98P) of PSTPIP2 in mice led to pathophysiological changes similar to CRMO, called chronic multifocal osteomyelitis in mice with increased IL-1β secretion in neutrophils and the inflammasome-independent IL-1β-mediated autoinflammatory reactions." (PMID 25956236, 2015). "This review outlines the mechanisms of PSTPIP2 in chronic multifocal osteomyelitis (CMO), rheumatoid arthritis (RA), synovitis-acne-pustulosis-hyperostosis-osteitis (SAPHO) syndrome, liver diseases, renal diseases, pressure ulcer sepsis and diabetic obesity." (PMID 39660128, 2024). "This chapter delves into the pivotal role of PSTPIP2 protein in chronic multifocal osteomyelitis (CMO)." (PMID 39660128, 2024).
osteomyelitis (7 papers, 2015 to 2025). An acute or chronic inflammation of the bone and its structures due to infection with pyogenic bacteria. "The Pstpip2cmo mouse strain is among the best characterized of these; it harbors a mutation resulting in the loss of adaptor protein PSTPIP2 and development of autoinflammatory osteomyelitis." (PMID 34461100, 2021). "The missense mutations in PSTPIP2 leaded to osteomyelitis and osteopathy with bone deformities in mice." (PMID 34262554, 2021). "Here, we observed that Morrbid and Pstpip2 are co-expressed in mature myeloid cells and hypothesize a pathogenic role for Morrbid in osteomyelitis." (PMID 40503910, 2025). "We generated double-knockout (DKO) mutants, Pstpip2−/−Morrbid−/− to investigate the involvement of Morrbid in osteomyelitis." (PMID 40503910, 2025). "This review comprehensively examines the mechanisms of PSTPIP2 in diverse diseases, with a particular emphasis on its advancements in osteomyelitis, arthritis, SAPHO syndrome, hepatic diseases, renal diseases, and other inflammatory conditions." (PMID 39660128, 2024). "PSTPIP2, a crucial mediator in autoinflammatory diseases, can initiate or exacerbate the symptoms of osteomyelitis when absent or mutated." (PMID 39660128, 2024). "Pstpip2cmo mice express a Leu98Pro missense mutation in the Pombe Cdc15 homology family protein proline serine-threonine phosphatase interacting protein 2 (PSTPIP2) and develop osteomyelitis when they are fed a normal, low-fat diet." (PMID 26549942, 2015).
Hepatic fibrosis (5 papers, 2020 to 2024). The presence of excessive fibrous connective tissue in the liver. "Among the 26 liver fibrosis-related genes verified, 130 CpG sites in the CpG islands of the PSTPIP2 gene are significantly hypermethylated, and the expression of PSTPIP2 is significantly reduced." (PMID 34276405, 2021). "Recent studies have shown that PSTPIP2 also plays important roles in liver fibrosis and cisplatin-induced acute kidney injury, and is a predictive target for many other diseases, such as tuberculosis and asthma." (PMID 34262554, 2021). "The previous research of our group indicated that adding PSTPIP2 expression alleviated liver fibrosis and hepatic inflammation in mice." (PMID 34262554, 2021). "Thus, inhibition of PSTPIP2 methylation provides a promising approach for therapeutic interventions to prevent or treat liver fibrosis, liver inflammation and related diseases." (PMID 37056286, 2023). "Furthermore, PSTPIP2 may be a potentially critical factor in regulating macrophage polarization in hepatic fibrosis." (PMID 37056286, 2023). "And PSTPIP2 is enriched in M2-type macrophages, which produce many anti-fibrotic factors, such as IL-10, much more than the small number of fibrotic factors, such as TGF-β and IL-13, that are produced, reducing the inflammatory response and improving liver fibrosis." (PMID 37056286, 2023).
Sepsis (5 papers, 2019 to 2024). Sepsis is defined as life-threatening organ dysfunction caused by a dysregulated host response to infection. "They found that patients with sepsis due to pressure ulcers had lower levels of PSTPIP2 in their peripheral blood." (PMID 39660128, 2024). "PSTPIP2 exhibits anti-inflammatory effects in pressure-sore sepsis." (PMID 39660128, 2024). "The qPCR results suggest that GK and PFKFB3 might contribute to the progression of S. aureus-induced sepsis, and CEACAM1, TNFAIP6, PSTPIP2, SOCS3, and IL18RAP might be closely linked with E. coli-induced sepsis." (PMID 31093495, 2019). "The qPCR results suggested that GK and PFKFB3 might contribute to the progression of S. aureus-induced sepsis, and GK, CEACAM1, TNFAIP6, PSTPIP2, SOCS3, and IL18RAP might be closely linked with E. coli-induced sepsis." (PMID 31093495, 2019). "qPCR results suggested that PSTPIP2 may be closely related to Escherichia coli-induced sepsis." (PMID 35345523, 2022).
Arthritis (4 papers, 2018 to 2024). Inflammation of a joint. "Emerging research has shown that PSTPIP2 can inhibit osteoclast development and thereby prevent the onset of arthritis." (PMID 39660128, 2024). "Yao Y conducted a study utilizing an arthritis animal model to investigate the function of PSTPIP2 in FLS and demonstrated that PSTPIP2 exerts inhibitory effects on FLS proliferation and inflammatory responses." (PMID 39660128, 2024). "The distribution of PSTPIP2 in the knee joint cavity was scattered and the level was low during the peak inflammatory phase of arthritis, but the distribution became concentrated and the level became high during remission." (PMID 36324152, 2022). "In this study, we selected adjuvant-induced arthritis (AIA) as animal model to study the role of PSTPIP2 in FLSs." (PMID 30564127, 2018). "In this study, we analyzed the effect of PSTPIP2 on the inflammatory response and proliferation of FLSs in experimental arthritis model in vitro." (PMID 30564127, 2018).
SAPHO syndrome (4 papers, 2020 to 2025). SAPHO syndrome (acronym for Synovitis, Acne, Pustulosis, Hyperostosis and Osteitis) is an auto-inflammatory disease, mainly characterized by the association of neutrophilic cutaneous involvement and chronic osteomyelitis. "Therefore, further research is imperative to unravel and elucidate the underlying mechanistic connections between PSTPIP2 and SAPHO syndrome." (PMID 39660128, 2024). "Notably, inflamed tissues exhibited significant elevations in chemokines attracting neutrophils and IL-1β, hinting at a potential role for PSTPIP2 in innate immunity and autoinflammatory bone diseases, possibly linked to the pathogenesis of human SAPHO syndrome." (PMID 39660128, 2024). "PSTPIP2 knockout mice (PSTPIP2-/-) have been reported to develop paw swelling, synovitis, osteoproliferation, and osteitis, similar to SAPHO syndrome." (PMID 34262554, 2021). "Several other genes, such as PSTPIP2, NOD2, and LPIN2, have been found to be associated with SAPHO syndrome, although have yet to be confirmed pathogenic." (PMID 33153463, 2020). "However, there are also different points of view, Hurtado-Nedelec M analyzed the PSTPIP2 gene in patients with SAPHO syndrome." (PMID 39660128, 2024). "We systematically outline the role of PSTPIP2 in CMO, RA, SAPHO syndrome, liver diseases, renal diseases, pressure ulcer sepsis and diabetic obesity." (PMID 39660128, 2024). "Two mutations encoding PSTPIP1 gene (A230T and E250Q) were found in PAPA patients, and the absence of PSTPIP2 triggers SAPHO syndromes." (PMID 34262554, 2021).
acute kidney injury (3 papers, 2020 to 2024). Sudden and sustained deterioration of the kidney function characterized by decreased glomerular filtration rate, increased serum creatinine or oliguria. "Our findings indicated that neutrophils and NETs play a key role in AAN and therapeutic targeting of PSTPIP2/NF-κB/IL-19/IL-20Rβ might extend novel strategies to minimize Aristolochic acid I-mediated acute kidney injury and apoptosis." (PMID 38314821, 2024).
inflammatory bone diseases (3 papers, 2018 to 2022). "PSTPIP2, a protein associated with auto-inflammatory disease, which is involved in macrophage activation, neutrophil motility, and osteoclast differentiation, has been recently proposed to play a role in the development of auto-inflammatory bone disorders." (PMID 30564127, 2018). "However, more studies have been reported to reveal the role of PSTPIP2 in inflammatory bone diseases." (PMID 36324152, 2022).
rheumatoid arthritis (3 papers, 2022 to 2025). A chronic, systemic autoimmune disorder characterized by inflammation in the synovial membranes and articular surfaces. "Kyoto Encyclopedia of Genes and Genomes (KEGG) enrichment analysis of GMP2 and Cxcl2_NE, and GO analysis of OMC, showed that the pathways and functions of cell metabolism, rheumatoid arthritis and osteoclast differentiation were significantly upregulated in Pstpip2−/− compared to WT and DKO mice." (PMID 40503910, 2025). "This suggests that locally regulating PSTPIP2 expression in the joint microenvironment may be a potential strategy for controlling rheumatoid arthritis bone erosion." (PMID 39660128, 2024). "They discovered that PSTPIP2 regulates synovial macrophage polarization and dynamics through Estrogen Receptor Beta, forming an immune barrier (F4/80(+)PSTPIP2(hi) cell-enriched zone) at the joint, thereby controlling rheumatoid arthritis bone erosion." (PMID 39660128, 2024). "Thus, local modulation of PSTPIP2 expression in the joint cavity may be a potential strategy for controlling bone erosion in rheumatoid arthritis." (PMID 36324152, 2022). "Thus, local modulation of PSTPIP2 expression in the joint microenvironment may be a potential strategy for controlling bone erosion in rheumatoid arthritis." (PMID 36324152, 2022).
acne (2 papers, 2022). An inflammatory process of the sebaceous glands which is characterized by comedones, nodules, papules and/or pustules on the skin. "Interestingly, PEST-PTPs play an important role in another autoinflammatory disorder named PAPA syndrome (pyogenic sterile arthritis, pyoderma gangrenosum, and acne) which is caused by the loss of their binding to PSTPIP1, a homologue of PSTPIP2." (PMID 36605205, 2022).
AIDS (2 papers, 2021 to 2022). A syndrome resulting from the acquired deficiency of cellular immunity caused by the human immunodeficiency virus (HIV). "It has been reported that mutation of PSTPIP2 gene in mice can lead to the occurrence of macrophage-mediated AIDs." (PMID 34262554, 2021). "PSTPIP2 is known to play an important role in the development of AIDs, where its reduced or complete loss of expression is the major cause of the diseases." (PMID 34262554, 2021). "In recent years, PSTPIP2 has been found to play an important role in congenital immune diseases and acquired immune diseases (AIDS)." (PMID 35345523, 2022). "PSTPIP2 may be a potential target for the treatment of AIDs, providing a new theoretical support for the treatment of AIDs." (PMID 34262554, 2021). "There is evidence that PSTPIP2 plays an important role in the development of AIDs." (PMID 34262554, 2021). "PSTPIP2 might play a vital role in the development of AIDs, and knowledge of these mechanisms will be useful for therapies for AIDs." (PMID 34262554, 2021). "This article reviews the research progress and mechanisms of PSTPIP2 in AIDs." (PMID 34262554, 2021). "Accumulating evidence suggests that PSTPIP2 of the F-BAR family plays a vital role in AIDs, they may be involved in controlling inflammation and the pathophysiology of some autoinflammatory syndromes." (PMID 34262554, 2021). "PSTPIP2 also provides a new therapeutic target for the treatment of AIDs." (PMID 34262554, 2021). "However, there are few studies on the role of PSTPIP2 in AIDs." (PMID 34262554, 2021). "In summary, PSTPIP2 may be a potential therapeutic target for AIDS." (PMID 34262554, 2021).
aristolochic acid nephropathy (2 papers, 2024). "PSTPIP2 expression was decreased in the aristolochic acid I (AAI)-induced acute aristolochic acid nephropathy model in vivo and injured mouse renal tubular epithelial cells (mRTECs) in vitro." (PMID 38314821, 2024).
autoimmune disease (2 papers, 2021 to 2024). A disorder resulting from loss of function or tissue destruction of an organ or multiple organs, arising from humoral or cellular immune responses of the individual to their own tissue constituents. "PSTPIP2 plays a crucial role in autoimmune diseases and is involved in macrophage activation, neutrophil migration, and cytokine production." (PMID 38314821, 2024). "It has been reported that PSTPIP2 suppressed inflammation in autoimmune diseases." (PMID 34262554, 2021). "PSTPIP2 may be closely related to autoimmune diseases and inflammation-related diseases." (PMID 34262554, 2021).
Obesity (2 papers, 2023 to 2024). Accumulation of substantial excess body fat. "In the realm of diabetic obesity, PSTPIP2 also alleviates obesity-related tissue inflammation in diabetic mice." (PMID 39660128, 2024). "We also identified CpGs and genes with links to obesity (NTRK2, PSTPIP2, MBIP) and glucose and fat metabolism (IRS1)." (PMID 37649101, 2023).
actinopathies (1 paper, 2021). "And it is speculated that PSTPIP2 may play an important role in actinopathies." (PMID 34262554, 2021).
alcoholic liver diseases (1 paper, 2022). A disorder caused by damage to the liver parenchyma due to alcohol consumption. "And methylation of PSTPIP2 is associated with hepatic macrophage polarization in alcoholic liver disease." (PMID 36324152, 2022).
allergic asthma (1 paper, 2023). A asthma with a basis in a pathological type I hypersensitivity reaction. "Upregulation of PSTPIP2 has also been linked to neutrophilic airway inflammation and non-allergic asthma." (PMID 37649101, 2023).
COVID-19 (1 paper, 2025). A disease caused by infection with severe acute respiratory syndrome coronavirus 2. "GNB1 showed the largest increase in the plasma of PLWH with COVID-19, followed by PTPN6, FERMT3, and PSTPIP2." (PMID 40568587, 2025).
E. coli infection (1 paper, 2019). "As for the eight common genes screened out in all four datasets, CEACAM1, GK, PFKFB3, and TNFAIP6 emerged repeatedly in the S. aureus group, but CEACAM1, IL18RAP, LILRA5, PFKFB3, PSTPIP2, and SOCS3 emerged in the E. coli infection." (PMID 31093495, 2019).
fibrosis (1 paper, 2024). the formation of excess fibrous connective tissue in an organ or tissue in a reparative or reactive process. "They discovered that increased PSTPIP2 expression alleviates hepatic fibrosis and inflammation in mice by modulating macrophage polarization." (PMID 39660128, 2024).
kidney damage (1 paper, 2024). "Serum Cr and BUN showed that Pstpip2 overexpression prevented renal dysfunction in AAI-induced nephropathy (n = 6 per group)." (PMID 38314821, 2024). "Pstpip2-cKI attenuates aristolochic acid I (AAI)-induced kidney damage." (PMID 38314821, 2024). "PSTPIP2 affected NET formation by regulating IL-19 expression via inhibition of NF-κB pathway activation in RTECs, inhibiting RTEC apoptosis, and reducing kidney damage." (PMID 38314821, 2024).
lentivirus infection (1 paper, 2021). Virus diseases caused by the Lentivirus genus. "PSTPIP2 overexpression was achieved by lentivirus infection." (PMID 33939302, 2021).
liver disease (1 paper, 2024). "Firstly, the intricate mechanisms of PSTPIP2 in diverse diseases remain incompletely understood, particularly its dual and sometimes paradoxical roles in different liver disease manifestations." (PMID 39660128, 2024). "This chapter emphasizes the multifaceted nature of PSTPIP2 in liver disease, suggesting its potential application in therapeutic strategies and the need for further research." (PMID 39660128, 2024).
pulmonary sarcoidosis (1 paper, 2022). Sarcoidosis affecting the lung parenchyma. "In addition to lymphocytes, PSTPIP2, a gene supposed to be associated with autoinflammatory processes of macrophages in a mouse model, was found to be upregulated in progressive fibrotic pulmonary sarcoidosis." (PMID 36203777, 2022).
rheumatic diseases (1 paper, 2024). "With the exploration of PSTPIP2, it has been discovered to play an inhibitory role in immune diseases, suggesting its potential utility in the research and treatment of rheumatic diseases." (PMID 39660128, 2024).